HIF1A (hypoxia inducible factor 1 subunit alpha)
Diseases named in the same sentence as HIF1A in open-access papers (continued):
Sharing a sentence is not in itself a finding about the gene and the disease.
tumor (continued). "Therefore, VEGF, Tie-2, and the hypoxia-inducible factor 1-α subunit (HIF-1α) are the most potent pro-angiogenic factors, and their over-expression in tumor cells promotes tumor growth in animal models by inducing angiogenesis." (PMID 24223741, 2013). "In light of these discrepancies among different tumours there may be tissue-specific differences in response to HIF-1α regulation." (PMID 23599780, 2013). "These authors confirmed that the cytotoxic machinery of CD8 T cells was functional at low oxygen levels and that the decrease in killing could be explained by HIF-1α mediated resistance of the tumor cells." (PMID 23724099, 2013). "Activated T cells and many tumor cells, therefore, can exhibit elevated levels of HIF1α." (PMID 24280044, 2013). "However, we found that HIF-1α overexpression completely abrogated the inhibitory effects of high AA on tumor growth and neoangiogenesis in vivo and significantly diminished the induction of apoptosis by high AA in the leukemic cells in vitro." (PMID 23626851, 2013). "Moreover, it has been demonstrated that experimentally induced overexpression of HIF-1α in cells of non-small-cell pulmonary carcinoma (line A549) inhibits tumour development, i.a., through a more pronounced apoptosis." (PMID 24153191, 2013). "The increased expression of HIF-1α is very common in a variety of human tumors and some precancerous lesions, indicating that its expression may be an early event in tumor progression." (PMID 23984913, 2013). "HIF-1α is the main active subunit, which can induce a vast array of gene products that control energy metabolism, neovascularization, survival and cell migration and is a strong promoter of tumor growth." (PMID 23732337, 2013). "Alternatively, YC-1-mediated downregulation of PR could play a key role in the anti-tumor effectiveness of this HIF-1α inhibitor, a possibility which remains to be tested." (PMID 23123638, 2013). "Such immunosuppressive activity of HIF-1α could play a detrimental role in tumour microenvironment inhibiting the anti-tumoural immune response of T cells." (PMID 23551576, 2013). "HIF-1α expression was found to significantly correlate with tumor size and differentiation degree." (PMID 24260057, 2013). "Notably, HIF-1α miRNA used in our experiments inhibited tumor growth more effectively than survivin RNA interference, as shown in a previous study." (PMID 23732337, 2013). "Although expression of HIF1α was heterogeneous in tumor sections it would be difficult in the current study to predict whether up regulation of HIF1α is hypoxia-dependent or -independent (normoxic)." (PMID 23342109, 2013). "A well studied and used proteasome inhibitor is Bortezomib (also mentioned as HIF1α inhibitor) that has been shown to reduce tumor growth in xenograft models and has been successfully used in first-line therapy in combination with other drugs such as cisplatinum." (PMID 23408731, 2013). "The expression of HIF-1α was determined to be of prognostic relevance in different tumours." (PMID 23599780, 2013). "Hypoxia-induced HIF-1α also promotes tumor progression by promoting immune evasion." (PMID 23673510, 2013). "Further extending the current knowledge on the complex regulation of VEGF, our data suggest that GPER may contribute to the HIF-1α mediated transcriptional responses in hypoxic tumor microenvironment towards new blood vessel formation." (PMID 23947803, 2013). "HIF-1α is a major regulator in tumor progression and metastasis which responds to hypoxia." (PMID 24015181, 2013). "However, based on a review of the literature, the prognostic relevance of HIF-1α in tumours derived from squamous epithelium remains controversial." (PMID 23599780, 2013). "HIF1α also promotes tumor radioresistance through stimulation of endothelial cell survival." (PMID 24216979, 2013).
tumor (continued). "In this stage cancer cells are under greater hypoxia and oxidative stress, in which many transcription factors, such as HIF-1α and NFκB, are activated leading to transmit aberrant signals resulting in abnormal functions such as tumor angiogenesis, cancer invasiveness and metastasis." (PMID 23638734, 2013). "BBR might function through inactivating PI3K/AKT and Raf/MEK/ERK signaling pathway, inhibiting the phosphorylation of Akt and ERK proteins, and downregulating HIF-1α signaling to inhibit tumor cell growth." (PMID 23869238, 2013). "However, there was an increase in the positive rate of HIF-1α with depth of tumor invasion (P = 0.013)." (PMID 23723999, 2013). "It has been demonstrated that HIF-1α expression has a significant effect on tumor progression." (PMID 24137322, 2013). "A growing body of evidence has proved that inhibition of neovascularization via suppressing HIF-1α/VEGF/VEGFR2 signaling pathway may delay tumor progression and perhaps even starve tumor cells to death." (PMID 23951172, 2013). "Moreover, miR-210 has been described as a key regulator of the hypoxia response in tumor onset identified as a major HIF1A-induced miRNA, and makes link between hypoxia and the regulation of cell cycle." (PMID 23848554, 2013). "HIF1-α is a known tumor-promoting transcription factor in most malignancies; however, its expression in tumor stromal fibroblasts could suppress cancer cell growth." (PMID 23937926, 2013). "This HIF-1α-dependent bioenergetic flexibility may confer an adaptive advantage to cancer cells as they are exposed to the ever-changing landscape of tumor microenvironment." (PMID 23840849, 2013). "Multiple xenograft tumour models also support the hypothesis that HIF1α and HIF2α play different roles in tumor progression by regulating both shared and unique target genes." (PMID 24324596, 2013). "Similarly, positive correlations were disclosed between tumour’s malignancy grade and expression of Ki-67 proliferation antigen (r = 0.61; P < 0.0001), and between expressions of HIF-1α and Ki-67 (r = 0.43; P < 0.0005)." (PMID 24153191, 2013). "Another important pathway in mitochondrial dysfunction involved in tumour progression is HIF-1α." (PMID 23762063, 2013). "Tumor cells adapt to exist in these hypoxic microenvironments by up-regulating pro-survival mechanisms, the majority of which are coordinated by the transcription factor hypoxia inducible factor-1 α (HIF-1α)." (PMID 24860738, 2013). "Among the tested markers, HIF-1α and c-Met were involved in lymph node metastasis and tumor stage." (PMID 23927384, 2013). "Both heme and hypoxia activate HIF-1α in tumor cells which, in turn, stimulates synthesis of HO-1." (PMID 23326340, 2013). "In our study we have analogously found that HIF-1α expression has manifested positive correlation with certain prognostically unfavourable traits of the tumours, i.e., with malignancy grade and proliferative potential, reflected in expression of the Ki-67 antigen." (PMID 24153191, 2013). "Higher levels of HIF1α and VEGF are associated with increased risk of tumor metastasis." (PMID 23123638, 2013). "Therefore, factors whichever influence the quantity and/or activity of HIF-1A will definitely affect the onset and fate of tumor cells." (PMID 23723982, 2013). "EZN-2968 is a LNA directed against HIF1α that has shown great inhibition of HIF1α and HIF1α-dependent genes and that is currently under phase I clinical study because of its ability to reduce tumor growth in xenografts." (PMID 23408731, 2013). "In positive cases, HIF-1α immunoreactivity was present in the cytoplasm of tumor cells." (PMID 24260057, 2013). "Results of this study indicate a similar biological role of HIF-1α in dogs and in humans, which may confirm suitability of the animal model in investigations on progression of tumours in humans." (PMID 24153191, 2013).
tumor (continued). "This contradiction may be due to a uniform cut-off point of HIF-1α expression or various types of tendentious treatment for the tumor." (PMID 23251251, 2013). "The PI3K-Akt-HIF-1α-VEGFA pathway plays an important role in tumor angiogenesis." (PMID 24194905, 2013). "Furthermore, re-expression of HIF-1α in SUM149-shECad clones rescued the tumor growth defect in vivo." (PMID 23530113, 2013). "HIF-1α controls the transcriptional activation of a variety of genes in the divergent signaling pathways involved in cell proliferation, survival, energy metabolism as well as tumor metastasis and angiogenesis." (PMID 24349381, 2013). "HIF1α expression in CRPCs possibly contributes to chemo-resistance and tumor metastasis." (PMID 23342109, 2013). "Since a major feature of solid tumors is hypoxia, it is well accepted that tumor elicits an angiogenic response mainly as a result of a HIF-1α-driven increase in angiogenic factor expression, even if dysregulation, due to intrinsic genetic mutations, must also be taken into account." (PMID 23555666, 2013). "Hypoxia may also render the tumor cells more resistant to cytotoxic T lymphocyte (CTL)-mediated lysis through HIF-1α-dependent induction in cancer cells of miR-210, which downregulates the expression of PTPN1, HOXA1, and TP53I11 genes." (PMID 24062984, 2013). "HIF-1α was found to be frequently overexpressed in tumours in a hypoxia-independent manner." (PMID 23599780, 2013). "Our results suggest that HIF-1α provides a high degree of bioenergetic flexibility under different OT which may confer an adaptive advantage for BCC survival in the tumor microenvironment and during invasion and metastasis." (PMID 23840849, 2013). "We have observed that the majority of ASCs in the tumor-bearing tissue are either double-positive or double-negative for HIF-1α and aromatase expression, suggesting an association between the two proteins." (PMID 23566437, 2013). "In untreated tumor HIF-1α was expressed at low levels in the cytoplasm and nucleus of most tumor cells but was strongly expressed in the nucleus of a proportion of cells interspersed throughout the tumor (control arrows)." (PMID 24403226, 2013). "The HIF-1α expression in mammary adenomas and adenocarcinomas of bitches may indicate that the biological role of the protein is similar in tumours of canines and humans." (PMID 24153191, 2013). "HIF1α, a potential tumor hypoxic marker, is a key cellular survival protein during hypoxia." (PMID 23671581, 2013). "RT-PCR was used to detect expression of HIF-1α mRNA and survivin mRNA in tumor tissues." (PMID 23732337, 2013). "Tumor cells might depend on HIF-1α to sustain viability by promoting autophagy during tumorigenesis as well as during therapy." (PMID 24312289, 2013). "We suspect that different tumor cells and different stimuli may result in HIF-1α showing different effects on survivin gene expression under normoxia." (PMID 23732337, 2013). "In this study, we attempted to capitalize on in vitro data suggesting that mTOR inhibition could enhance tumor cell killing by DNA damaging agents such as irinotecan through the HIF-1α pathway." (PMID 24216984, 2013). "While NAC prevented Hif-1α stabilization under hypoxia in vitro and increased levels of glutathione in the blood of mice in vivo, this did not translate to a difference in tumor growth or the hypoxic state of the tumor compared to untreated control mice." (PMID 23840457, 2013). "Silencing HIF-1α also has been shown to reverse chemotherapy resistance in tumor cells." (PMID 23289374, 2013). "The assessment of HIF-1α expression in the LSCC tissues may be conducive to predicting the status of tumor progression and metastasis." (PMID 23946810, 2013).
tumor (continued). "During hypoxia of tumor cells, the upregulated hypoxia inducing factor (HIF)-1α forms a heterodimer with HIF-1β to become a transcription factor HIF-1 that activates pro-angiogenic genes such as vascular endothelial growth factor A (VEGFA), to promote angiogenesis for tumor growth and metastasis." (PMID 24013378, 2013). "It is accepted that in high-grade tumors the nutritional and oxygen demands per unit volume of tissue are higher, which it tries to compensate by stimulating various proangiogenic factors like hypoxia inducible factor (HIF-1α) that enhances the microvascular networks in the tumour." (PMID 24066240, 2013). "In addition, HIF-1α expression has been found to correlate significantly with tumor size and differentiation." (PMID 24260057, 2013). "HIF-1α inhibition blocks this evasive resistance and augments destruction of the tumor vasculature." (PMID 22684860, 2013). "The effect of VEGF inhibition on intratumoral hypoxia and HIF-1α activity may vary depending on the specific tumor type." (PMID 22684860, 2013). "Additionally, in the present study, HIF-1α and VEGF were mainly expressed in the TSCC tissue and were barely detected in the adjacent non-tumor tissue suggesting that HIF-1α was present and overexpressed in TSCC." (PMID 23251251, 2013). "In positive specimens HIF1α expression was homogeneous throughout the tumor area." (PMID 23342109, 2013). "Overexpression of HIF-1α occurs in a wide range of primary and metastatic cancers, and is responsible for a range of tumour-related properties including a reduction in reactive oxygen species, increased radio-resistance, and protection of cells from drug induced apoptosis and senescence." (PMID 23638097, 2013). "Upregulation of glucose transport due to increased GLUT1 expression was not an explanation for the different FDG uptakes observed, although tumor hypoxia and HIF1α expression may provide a reasonable mechanism." (PMID 23718763, 2013). "Perhaps, the better outcome in patients with high HIF-1α expressing tumors might be due to its inhibitory role on tumor cells through induction of proapoptotic pathway." (PMID 24165149, 2013). "Hypoxia-inducible factor-1α (HIF-1α) is considered a key regulator of tumor angiogenesis." (PMID 23802096, 2013). "In addition to hypoxia, other physiological and pathological factors, such as cytokines, growth factors, activated oncogenes and inactivated tumor suppressors can activate HIF-1α primarily by stimulating its mRNA expression or translation." (PMID 24312289, 2013). "In tumor cells, HIF-1α may also be regulated by other genetic factors, including oncogenes (Ras and PI3-K) or the loss of tumor suppressors [VHL or phosphatase and tensin homolog (PTEN)] even under aerobic conditions." (PMID 23833638, 2013). "In this context, our present data add a further mechanism through which the tumor microenvironment may promote angiogenesis, as the HIF-1α/GPER signaling was shown to mediate the up-regulation of VEGF expression in CAFs cultured in hypoxic conditions." (PMID 23947803, 2013). "Prolonged antiangiogenic therapy of tumors not only delays tumor growth but may also increase hypoxia and HIF-1α activity." (PMID 22684860, 2013). "The effects of DCA on tumor metastases in this study may be through inhibition of the redox-sensitive transcription factor HIF1α." (PMID 23471124, 2013). "Hypoxia-inducible factor1α (HIF-1α) plays an important role in the growth and metastasis of tumor." (PMID 24015181, 2013). "Additionally, post-DCA GBM tumor biopsies had decreased HIF1α expression and activity resulting in a significant decrease in tumor vascularity compared to pre-DCA GBM biopsies." (PMID 23471124, 2013). "Overexpression of HIF-1α is assumed to promote malignant transformation and tumor progression and thus might reduce the accessibility to radiotherapy." (PMID 22347438, 2012).
tumor (continued). "The tumor microenvironment is characterized by hypoxia, low pH, and high interstitial fluid pressure, all of which underlie exaggerated production of proangiogenic factors such as VEGF through HIF1α activation in the tumor milieu." (PMID 22187650, 2012). "The enhanced expression of VEGF165 by the hypoxia-primed HT1080 cells, the HIF-1α-dependent tubule formation seen in the earlier experiments and the formation of vessel-like structures by the tumour cells in vivo prompted us to look for the expression of NRP-1 in the hypoxia-primed cells." (PMID 23185562, 2012). "Nerve terminations were surrounded by tumor cells with high expression of HIF-1α and CX3CR1." (PMID 22952674, 2012). "Thus, PTEN inhibits tumor angiogenesis by suppressing HIF-1 activity through the reduction of the HIF-1α protein level." (PMID 23210979, 2012). "Moreover, higher HIF-1α immunoreactivity was related to the lower rate of complete remission of the primary tumor, lymph node metastases, local failure-free survival, disease-free survival, and overall survival." (PMID 23762617, 2012). "Moreover, decreased expression of miR-21 by anti-miR-21 transfection led to increased expression of PTEN, an endogenous inhibitor of Akt and ERK pathway, and inhibited tumor angiogenesis through the down-regulation of HIF-1α and VEGF in cancer cells." (PMID 23272057, 2012). "Recently, a link has been discovered between HIF-1α, tumour apoptosis, and the necrosis process." (PMID 22852079, 2012). "Recently, a relationship between HIF-1α, tumour migration and stem cell biology has been found." (PMID 22852079, 2012). "HIF-1α inhibition by siRNA also sensitized hypoxic human tumor cells to radiotherapy." (PMID 22804960, 2012). "We examined the distributions of HIF-1α expression and hypoxia in conjunction with blood perfusion in U251 tumor xenografts, in order to determine whether ER-400583-00 exerted antitumor activity against HIF-1α-expressing hypoxic cancer cells." (PMID 22211243, 2012). "HIF-1α is broadly expressed in many human cancers and frequently correlates with poor prognosis; it affects many key aspects of tumour initiation, progression, invasion, inflammatory cell recruitment and metastasis, and represents an attractive target for anti-cancer therapies as reviewed recently." (PMID 22424533, 2012). "Interestingly, we found that vemurafenib treatment in mice bearing drug-resistant A375 xenografts also induced increased FDG tumor uptake, accompanied by increases in Hif-1α, Sp1 and Ksr protein levels." (PMID 22651703, 2012). "Moreover, basic research has demonstrated that tumor growth after radiation therapy was significantly delayed when an adenovirus expressing siRNA targeting HIF-1α was administered." (PMID 23203043, 2012). "Furthermore, novel hypoxia/HIF-1α-regulated targets that can mediate metastasis will need to be identified in order to complete the full picture of tumor metastasis induced by hypoxia/HIF-1α." (PMID 23241400, 2012). "HIF1α is known to play a role in promoting tumor cell’s apoptosis." (PMID 22546016, 2012). "PTEN is a tumor suppressor which dominates the PTEN/HIF-1α pathway." (PMID 23391506, 2012). "Importantly, this hypoxia-induced, KLHL20-mediated PML ubiquitination pathway not only attenuates PML tumor suppressive functions but also participates in a feedback mechanism to maximize the production of HIF-1α during hypoxic stress." (PMID 22935031, 2012). "The PI3K pathway is known to facilitate tumor angiogenesis by increasing the HIF-1α level." (PMID 23210979, 2012). "Tumour cells were positive for CK, S-100 protein, Glut-1, HIF-1α, PI3K and p-Akt." (PMID 22551172, 2012). "Based on these results, we hypothesize that K5 might inhibit cancer progression such as growth and metastasis by the dual effects of anti-angiogenesis and suppression of tumor cell motility, and involving in the regulation of HIF-1α pathway." (PMID 23300882, 2012).